CFAP20DC (CFAP20 domain containing)
Synonyms: C3orf67; FLJ42117; FLJ42930
Tractability: No criterion of Open Targets' tractability assessment is met for any kind of drug.
Gene: Protein-coding gene on chromosome 3 (58,717,365 to 59,050,084, reverse strand). Ensembl gene ENSG00000163689.
Subcellular location (Human Protein Atlas): Golgi apparatus
Genetic constraint (gnomAD): Loss-of-function variants: 47 observed, 67.06 expected, observed/expected ratio (o/e) 0.7, 90% interval 0.55 to 0.89. The upper end of that interval is the gene's LOEUF score, 0.89, which puts it in group 3 of 6, group 1 being the genes least tolerant of losing a copy. Missense variants: 714 observed, 741.33 expected, observed/expected ratio (o/e) 0.96, 90% interval 0.9 to 1.02. Synonymous variants: 269 observed, 274.76 expected, observed/expected ratio (o/e) 0.98, 90% interval 0.88 to 1.08.
Homologues: Orthologues: chimpanzee CFAP20DC (99% identical), macaque CFAP20DC (96% identical), dog CFAP20DC (82% identical), pig CFAP20DC (81% identical), rabbit CFAP20DC (79% identical), guinea pig CFAP20DC (70% identical), mouse Cfap20dc (65% identical), rat Cfap20dc (65% identical), tropical clawed frog cfap20dc (46% identical), zebrafish cfap20dc (36% identical). Paralogues in human: CFAP20 (6% identical).
Diseases named in the same sentence as CFAP20DC in open-access papers:
CFAP20DC is named in the same sentence as 2 diseases in open-access papers, as found by Europe PMC text mining. Sharing a sentence is not in itself a finding about the gene and the disease.
CFAP20DC shares sentences with these, for which no sentence is quoted: tumor (2 papers); glioma (1).